FOXF2 (forkhead box F2)
Diseases named in the same sentence as FOXF2 in open-access papers (continued):
Sharing a sentence is not in itself a finding about the gene and the disease.
prostate carcinoma (continued). "FOXF2 was found highly expressed in benign prostatic hyperplasia and the transition zone of the normal prostate, where less suffer prostate cancer." (PMID 25848863, 2015). "Since we focused on three target genes (RECK, MTSS1 and FOXF2) and investigated only 52 clinical samples, additional studies will be needed to elucidate the role of miR-182-5p in prostate cancer and its use in clinical applications." (PMID 23383207, 2013). "The decreased expression of FOXF2 has been reported in prostate cancer." (PMID 37705744, 2023). "Since increased stromal Foxf2 expression enhances T-cell infiltration in several prostate cancer models, we reasoned that increasing stromal Foxf2 activity can enhance the response of prostate cancer to ICIs." (PMID 36369237, 2022). "Based on these observations and arguments, increasing Foxf2 expression alone or in combination with immunotherapies could be a therapeutic strategy for prostate cancer." (PMID 36369237, 2022). "We employed the Transgenic Adenocarcinoma of the Mouse Prostate (TRAMP) mouse model for prostate cancer to determine whether stromal Foxf2 affected tumor progression." (PMID 36369237, 2022). "We further investigated whether a higher stromal FOXF2 expression in human prostate cancer specimens correlates to a more immunocompetent tumor microenvironment." (PMID 36369237, 2022). "Additionally, in prostate cancer, FOXF2 has an opposite regulatory effect with TGFβ3 pathways, which is described as triggering EMT via MMP-dependent mechanisms." (PMID 27487137, 2016). "In prostate cancer, FOXF2 mRNA was decreased compared to normal prostate tissues, and it is a potential target genes of miR-182-5p, which promotes cell invasion and proliferation by down- regulating FOXF2, RECK and MTSS1 genes." (PMID 27487137, 2016). "Additionally, Forkhead Box 2 (FOXF2) is a transcription factor that is important for many cellular functions and its expression is decreased in prostate cancer." (PMID 25799167, 2015). "In our study, FOXF2 knock down increased cell invasion and migration in prostate cancer cell lines." (PMID 23383207, 2013). "Therefore, we sought to investigate whether and how stromal Foxf2 affects prostate cancer progression." (PMID 36369237, 2022). "Another study reported that three genes, FOXF2, RECK, and MTSS1, which act as tumor suppressors and are involved in inhibiting the development of prostate cancer cells by reducing invasion and migration, were targeted by miR-182-5p." (PMID 37438760, 2023). "In prostate cancer, MMP1 was down-regulated by FOXF2 whereas TIMP3, one of MMPs inhibitors, was up-regulated by FOXF2." (PMID 27487137, 2016). "To determine whether increasing stromal Foxf2 expression affects prostate cancer cell growth in vitro, we cocultured the control and Foxf2-expressing mPrSC and WPMY-1 cells with mouse and human prostate cancer cells, respectively." (PMID 36369237, 2022). "Additionally the levels of FOXF2, RECK and MTSS1 were significantly higher in xenograft tissues from low miR-182-5p expressing prostate cancer cells." (PMID 23383207, 2013). "Also knock down of miR-182-5p in order to increase expression of tumor suppressor genes FOXF2, RECK and MTSS1 may be of therapeutic benefit in prostate cancer treatment." (PMID 23383207, 2013). "Additionally knocking down of miR-182-5p with inhibitor may be of therapeutic benefit for enhancing expression of tumor suppressor genes FOXF2, RECK and MTSS1 in prostate cancer cells." (PMID 23383207, 2013).
cleft palate (10 papers, 2016 to 2024). Cleft palate is a fissure type embryopathy that affects the soft and hard palate to varying degrees. "When detailing their amino acid alignments, its polyprotein showed matches with Forkhead Box F2; Nasreddine, El hajj, and Ghassibe-Sabbagh (2021) presented two proteins from the same family as being associated with cleft palate." (PMID 38675854, 2024). "Heterozygous FOXF2 variants in humans have been associated with cleft palate, which has also been seen in Foxf2 -/- mice." (PMID 36964621, 2023). "Disruption of FOXF2, encoding a member of the Forkhead family transcription factors, has been associated with cleft palate in humans and mice." (PMID 33898467, 2021). "Accordingly, Foxf2-deficient mice die shortly after birth due to cleft palate and abnormal tongue and gut development, indicating an essential role of Foxf2 in this EMT-associated developmental process." (PMID 30285803, 2018). "Mutations in FOXF2 have been associated with cleft palate in humans." (PMID 33898467, 2021). "Although cleft palate has been reported in mice deficient in Foxf2, whether Foxf2 plays an intrinsic role in and how Foxf2 regulates palate development remain to be elucidated." (PMID 26745863, 2016). "Mutations in FOXF2 have also been associated with cleft palate in humans." (PMID 26745863, 2016). "Therefore, modulating Wnt2b expression may lead to cleft palate treatment caused by Foxf2 gene defects." (PMID 35668101, 2022). "This comprehensive analysis revealed decreases in gene expressions associated with lung development; Foxa2, Notch1, Foxp2, Nkx2.1, and intestine development; Cdx2, Foxf2, Foxl1, and skeletal development; Hoxd12, Hoxd13, Scx, Brachyury, and cleft palate; Foxf2." (PMID 34671097, 2021). "Thus, better understanding of the molecular mechanisms mediating Foxf2 function in palate development in mice will improve our understanding of cleft palate pathogenesis in humans." (PMID 33898467, 2021). "We recently showed that neural crest-specific inactivation of either Foxf1 or Foxf2 caused cleft palate but did not significantly affect mandible and tongue development." (PMID 30638444, 2019). "We found that both Foxf2c/-Wnt1-Cre and Foxf2c/-Osr2IresCre/+ mice have complete penetrance of cleft palate and many of the mutant embryos showed failure of palatal shelf elevation, similar to the cleft palate phenotype in mice with constitutive inactivation of the Foxf2 gene (Foxf2-/-)." (PMID 26745863, 2016). "However, the majority of patients in our cohort with a deletion including FOXF2 did not have a cleft palate demonstrating reduced penetrance of this feature." (PMID 36964621, 2023). "Previous studies on FOXF2 found that mice lacking FOXF2 with cleft palates died perinatally because their oral cavity could not form negative pressure, leading to difficulties in sucking." (PMID 33717680, 2021).
gastric cancer (8 papers, 2019 to 2023). A primary or metastatic malignant neoplasm involving the stomach. "Consistently, FOXF2 inhibited the growth of gastric tumor cells in vivo, and epigenetic silencing of FOXF2 is associated with poor prognosis in stomach cancer patients." (PMID 34298659, 2021). "Methylation in the promoter region of another tumor suppressor FOXF2 has previously been associated with shorter survival in gastric cancer patients." (PMID 30987631, 2019). "FOXF2 deregulation ought to an aberrant DNA methylation status has also recently been identified for gastric cancer." (PMID 36900258, 2023). "In our set of genes, FOXD3 and FOXF2 have had a few studies performed on colon or gastric cancers." (PMID 30987631, 2019). "It was reported that si-FOXF2 stimulated WNT1 and β-catenin and further upregulated the Wnt target genes cyclin D and c-myc in a gastric cancer cell line." (PMID 33176855, 2020).
colorectal cancer (6 papers, 2019 to 2022). A primary or metastatic malignant neoplasm that affects the colon or rectum. "lncRNA MCM3AP-AS1 is reported to restrain the development of colorectal cancer through mediating miR-19a-3p/FOXF2 signaling." (PMID 34446088, 2021). "MiR-19a-3p could regulate the Forkhead box F2-mediated Wnt/β-catenin signaling pathway and affect the biological functions of colorectal cancer cells." (PMID 34895042, 2021).
ischemic stroke (3 papers, 2016 to 2025). A stroke disorder caused by obstruction of blood flow to the brain, due to thrombotic (local blood clot formation) or embolic (due to a blood clot or other material traveling from another site) event. "Four tag SNPs and rs12204590 located in or near FOXF2 were selected, and the associations between genotypes/alleles and ischemic stroke were analyzed." (PMID 29163794, 2017). "By the genotype analysis, a novel SNP rs1711972, near FOXF2, was observed to be associated with an increased risk of ischemic stroke(CA genotype, adjusted OR = 1.35; 95% CI, 1.07 to 1.70), but not significantly after Bonferroni corrections for multiple tests." (PMID 29163794, 2017). "However, whether polymorphisms in FOXF2 are also associated with the incidence of ischemic stroke in other populations remains unknown." (PMID 29163794, 2017). "Several genes, including PITX2,ZFHX3, HDAC9, FOXF2,GUCY1A3, and GCH1, havebeen identified to increase the risk of developing ischaemic stroke." (PMID 40351662, 2025). "This is the first study to investigate the relationship between the SNPs in FOXF2 and ischemic stroke in Chinese Han population." (PMID 29163794, 2017). "In summary, we identified a novel FOXF2 SNP (rs1711972), which may be used as a candidate biomarker of ischemic stroke and LAA stroke in the Chinese Han population." (PMID 29163794, 2017).
ovarian carcinoma (3 papers, 2020 to 2021). A malignant neoplasm originating from the surface ovarian epithelium. "MiR183-96∼182 and lncRNA ADAMTS9-AS2 promoters, which block EMT by increasing FOXF2 expression, can be used as treatments for lung and ovarian cancer." (PMID 33717680, 2021). "lncRNA ADAMTS9-AS2 decreased tumour progression in ovarian cancer by regulating the miR-182-5p/FOXF2 axis." (PMID 34645493, 2021).
triple-negative breast carcinoma (3 papers, 2013 to 2016). An invasive breast carcinoma which is negative for expression of estrogen receptor (ER), progesterone receptor (PR), and human epidermal growth factor receptor 2 (HER2). "Our previous clinical study demonstrated that the under-expression of FOXF2 is associated with early-onset metastasis and poor prognosis of patients with triple-negative breast cancer." (PMID 25848863, 2015). "Due to the limited size of triple-negative cohort cases in this study, the validation of large samples and the prognostic evaluation of FOXF2 mRNA as a basal marker for triple-negative breast cancer patients needs to be investigated in the future." (PMID 23620774, 2013). "Taken together, we conclude that decreased FOXF2 expression indicates the early-onset metastasis and poor prognosis for patients with histological grade II and triple-negative breast cancer." (PMID 23620774, 2013). "Our data also demonstrate that patients with low FOXF2 mRNA levels have a high risk of early-onset relapse and metastasis, and FOXF2 mRNA levels independently predict DFS in patients with triple-negative breast cancer." (PMID 23620774, 2013). "In summary, we conclude that decreased FOXF2 mRNA level indicates early-onset metastasis and poor prognosis of patients with histological grade II and triple-negative breast cancer." (PMID 23620774, 2013). "The results showed that in patients with triple-negative breast cancers, FOXF2 mRNA level was an independent prognostic factor for DFS prediction, and the risk of recurrence and metastasis in FOXF2low patients was 6.8-fold (95% CI = 1.467–31.287) higher than in FOXF2high patients (P = 0.014)." (PMID 23620774, 2013). "Low FOXF2 mRNA levels could predict shorter disease-free survival for those patients with histological grade II and triple-negative breast cancer." (PMID 23620774, 2013).
cerebral infarction (2 papers, 2017 to 2022). An ischemic condition of the brain, producing a persistent focal neurological deficit in the area of distribution of the cerebral arteries. "The conditional deletion of FOXF2 in adult mice led to the development of cerebral infarction, reactive gliosis, and cerebral microhemorrhage." (PMID 29163794, 2017). "FOXF2 knockout mouse embryos have shown developmental defects in the BBB, and deletion of FOXF2 in adult mice results in cerebral infarction, reactive gliosis, and microhemorrhage." (PMID 36294301, 2022).
cerebral small vessel disease (2 papers, 2025 to 2026). Cerebral small vessel disease is the term currently used to pathological processes that affect the brain parenchymal circulation (arterioles, capillaries, and veins). "Deletion of FOXF2 in ECs, a major risk gene for cerebral small vessel disease, induced key features of BBB dysfunction, including compromised cell junction integrity and enhanced caveolae formation." (PMID 41398476, 2025).
cervical cancer (2 papers, 2018 to 2020). A primary or metastatic malignant neoplasm involving the cervix. "Similarly, we detected in this article that low FOXF2 expression was associated with poor outcomes of cervical cancer patients, and that overexpression of FOXF2 inhibited Hela cells proliferation, migration, and invasion in vitro and growth in vivo." (PMID 30249755, 2018). "In cervical cancer, OC, bladder cancer, GC and intestinal adenoma, FOXF2 is a cancer suppressor, while in RMS, it is a promoter." (PMID 32503970, 2020). "In the present study, we researched the expression level of FOXF2 in cervical cancer and its effect on cervical cancer cells proliferation, migration, and invasion." (PMID 30249755, 2018). "In short, this research explored that down-regulation of FOXF2 predicted poor outcomes of cervical cancer patients." (PMID 30249755, 2018). "As far as we know, there were rarely literatures to report the relationship between FOXF2 expression and cervical cancer." (PMID 30249755, 2018). "FOXF2 was dramatically down-regulated in cervical cancer patients, and low FOXF2 expression predicted poor outcomes of cervical cancer patients." (PMID 30249755, 2018). "High expression of FOXF2 inhibits the expression of target genes in the Wnt/β-catenin signalling pathway and β-catenin in the nucleus, thereby inhibiting the proliferation, invasion and migration of cervical cancer cells." (PMID 32503970, 2020). "Low FOXF2 expression predicted poor outcomes of cervical cancer patients." (PMID 30249755, 2018). "This article was aimed to study the FOXF2 effects on cervical cancer." (PMID 30249755, 2018). "Based on these findings, we speculated that FOXF2 might inhibit the development of cervical cancer by regulating Wnt signaling pathway, which might be a potential target for the diagnosis and treatment of cervical cancer." (PMID 30249755, 2018). "The inhibitory effect of FOXF2 on β-catenin, c-Myc, CyclinDl, MMP9, and Lgr5 will provide an important theoretical basis for the diagnosis and targetted therapy of cervical cancer." (PMID 30249755, 2018).
intracranial hemorrhage (2 papers, 2017 to 2025). Bleeding within the SKULL, including hemorrhages in the brain and the three membranes of MENINGES. "FOXF2 is expressed in murine pericytes, and FOXF2 knockout mice develop intracranial hemorrhage, perivascular oedema and a leaky blood-brain barrier, further highlighting the role of these transcription factors in CNS development and function." (PMID 28344652, 2017).
metastatic disease (2 papers, 2013 to 2015). "Taken together, these results indicate that FOXF2 deficiency enhances the metastatic ability of BLBC cells and leads to invasive and metastatic disease in vivo." (PMID 25848863, 2015).
non-small cell lung carcinoma (2 papers, 2016 to 2020). A group of at least three distinct histological types of lung cancer, including non-small cell squamous cell carcinoma, adenocarcinoma, and large cell carcinoma. "Forkhead box F2 (FOXF2) is relatively limited to the adult lung, but its contribution to non-small cell lung cancer (NSCLC) prognosis is unclear." (PMID 27487137, 2016). "In non-small cell lung cancer (NSCLC), FOXF2 plays an anticancer role." (PMID 32503970, 2020).
osteoporosis (2 papers, 2021 to 2022). A condition of reduced bone mass, with decreased cortical thickness and a decrease in the number and size of the trabeculae of cancellous bone (but normal chemical composition), resulting in increased fracture incidence. "This study uncovers a critical role of Foxf2 in the differentiation of MSCs into osteoblasts and provides insight into the pathogenesis associated with bone-related diseases such as osteoporosis and nonunion after fracture." (PMID 35668101, 2022). "Thus, from a clinical perspective, systemic or local suppression of FOXF2 expression may be a promising strategy for treating bone-related diseases such as osteoporosis and fractures." (PMID 35668101, 2022). "Furthermore, if the expression of FOXF2 can be systematically reduced by medication to promote bone formation, this strategy may be helpful in the treatment of bone-related diseases such as osteoporosis." (PMID 35668101, 2022). "The findings point to FOXF2 as a promising drug target for the treatment of osteoporosis, non-healing fractures and other bone-related disorders." (PMID 35668101, 2022).
atrial septal defect (1 paper, 2014). Interauricular communication is a congenital malformation characterized by a communication between the atrial chambers of the heart. "Compound haploinsufficiency for both Foxf1a and Foxf2 caused an atrial septal defect of the primum type, an atrioventricular septal defect characterized by absence of the dorsal mesenchymal protrusion." (PMID 25356765, 2014).
atrioventricular septal defects (1 paper, 2014). "Compound haploinsufficiency for Foxf1a and Foxf2 caused atrioventricular septal defects, demonstrating the biological relevance of this regulatory network." (PMID 25356765, 2014).
bone metastasis (1 paper, 2019). Transfer of a neoplasm from its primary site to bones. "The patients were divided into high FOXF2 mRNA level (FOXF2high) and low FOXF2 mRNA level (FOXF2low) groups, using the optimal cutoff value of FOXF2 mRNA expression for distinguishing bone metastasis-free survival (BMFS) statuses in overall cases and cases stratified by subtypes." (PMID 31222004, 2019). "Our findings suggest that the FOXF2-CTSK axis may be a potential target for the prevention and treatment of bone metastasis-caused osteolytic bone destruction." (PMID 31222004, 2019).
cerebrovascular disease (1 paper, 2025). "FOXF2 encodes a transcription factor primarily expressed in brain pericytes and endothelial cells (ECs); however, its mechanistic role in cerebrovascular disease remains unknown." (PMID 41398477, 2025).
cleft lip (1 paper, 2022). Congenital defect in the upper lip where the maxillary prominence fails to merge with the merged medial nasal prominences. "In this model of cleft lip, transcriptional profiling indicated that SHH pathway activity and Foxf2 expression corresponded with reduced mesenchymal cell proliferation in the medial nasal processes with Foxf2 being demonstrated to be a direct target of Shh signalling." (PMID 35226783, 2022).
congenital diaphragmatic hernia (1 paper, 2020). A posterolateral defect of the diaphragm that allows passage of abdominal viscera into the thorax, leading to respiratory insufficiency and persistent pulmonary hypertension with high mortality. "Changes in FOXF2 copy number may lead to the occurrence of congenital diaphragmatic hernia." (PMID 32582291, 2020).
endometrial cancer (1 paper, 2023). Primary or metastatic malignant neoplasm involving the endometrium (mucous membrane that lines the endometrial cavity). "Based on RNA‐seq and ATAC‐seq analyses, extracellular matrix (ECM) signaling and ECM‐related transcription factors, FOXF2, POU1F1, and RUNX1were identified to potentially be involved in CD163+ macrophage‐induced progestin insensitivity in endometrial cancer patients." (PMID 36373483, 2023).
glioma (1 paper, 2024). A benign or malignant brain and spinal cord tumor that arises from glial cells (astrocytes, oligodendrocytes, ependymal cells). "For instance, FOXQ1 and FOXF2 were highly expressed in glioma, FOXF1 in LUAD, and GATA4 in CHOL and LIHC, all consistent with previous studies." (PMID 39345334, 2024).